ETS1 (ETS proto-oncogene 1, transcription factor)
Diseases named in the same sentence as ETS1 in open-access papers (continued):
Sharing a sentence is not in itself a finding about the gene and the disease.
experimental autoimmune encephalomyelitis (2 papers, 2016 to 2022). An autoimmune demyelinating disease of the central nervous system that is produced experimentally in animals by the injection of homogenized brain or spinal cord in Freund's adjuvant. "The activity of transcription factor ETS1, which is highly expressed in endothelial cells (ECs) and responded to an inflammatory condition, is suppressed in the central nervous system (CNS) ECs in MS and its animal model experimental autoimmune encephalomyelitis." (PMID 35568723, 2022).
gastric adenocarcinoma (2 papers, 2015 to 2025). "ETS1 was located in the nucleus and was upregulated in gastric adenocarcinoma tumour tissues compared to normal stomach tissues." (PMID 41162582, 2025). "Levels of miR-23b in stomach adenocarcinoma samples were down-regulated, whereas those of Notch2 receptor, v-ets erythroblastosis virus E26 oncogene homolog 1 (Ets1), and E2F1 transcripts were up-regulated." (PMID 26041881, 2015). "The relative miR-23b levels were inversely proportional to the expressions of Notch2 receptor, E2F1, and Ets1 mRNAs in stomach adenocarcinoma specimens." (PMID 26041881, 2015). "Results showed that expressions of miR-23b were significantly down-regulated in numerous stomach adenocarcinoma samples compared with normal counterparts, whereas those of Notch2 receptor, E2F1, and Ets1 mRNAs were up-regulated." (PMID 26041881, 2015). "Levels of miR-23b were lower in stomach adenocarcinoma specimens than in their corresponding normal tissue counterparts, but those of Notch2 receptor, E2F1, and Ets1 mRNAs were higher." (PMID 26041881, 2015).
inflammatory bowel disease (2 papers, 2017 to 2023). A spectrum of small and large bowel inflammatory diseases of unknown etiology. "ETS1 has also been linked to CD, as it is highly expressed in CD4+ T-cells from patients with inflammatory bowel disease and promotes Th1-driven mucosal inflammation through cold-inducible RNA binding protein (CIRBP)." (PMID 37048094, 2023).
liver cirrhosis (2 papers, 2017 to 2022). "In the present study, we identify a liver cirrhosis TF—miRNA—mRNA network containing 49 TFs, many of which have been previously implicated in liver disease (e.g. ETS1, FOS, FOXP3, FOXA2, and GATA2)." (PMID 28355233, 2017). "The transcription factor -/lncRNA- microRNA-mRNA network we uncovered that results in immune-mediated liver cirrhosis is comprised of 5 core microRNAs (e.g., miR-203; miR-219-5p), 3 transcription factors (i.e., FOXP3, ETS1 and FOS) and 7 lncRNAs (e.g., ENTS00000671336, ENST00000575137)." (PMID 28355233, 2017). "Our results also uncovered several other TFs that may regulate the process of liver cirrhosis (e.g. FOXA1, RFX5, and ETS1) which are new potential targets for mechanistic studies of liver cirrhosis." (PMID 28355233, 2017).
metastatic cancer (2 papers, 2017 to 2020). A carcinoma which has spread from the original site of growth to another anatomic site. "MMP-9 is reported to be commonly over-expressed in metastatic cancer cells, progenitor cells, local inflammatory infections, acute hypoxia and physical trauma; its expression is regulated by VEGF through the expression of ETS-1 bound to the MMP-9 gene promoter." (PMID 32751717, 2020).
non-alcoholic steatohepatitis (2 papers, 2019 to 2021). "Studies have found that up-regulation of Ets-1 expression enhances transforming growth factor β (TGF-β)-induced hepatocyte apoptosis and accelerates liver inflammation and fibrosis in nonalcoholic steatohepatitis (NASH) mice." (PMID 34820381, 2021).
small cell lung carcinoma (2 papers, 2023). Small cell lung cancer (SCLC) is a highly aggressive malignant neoplasm, accounting for 10-15% of lung cancer cases, characterized byrapid growth, and early metastasis. "A study indicated that EGFR TKIs blocked Akt and Ets-1 activity and thus evoked gefitinib resistance in non–small-cell lung cancer cells." (PMID 37433225, 2023).
Stroke (2 papers, 2018). Sudden impairment of blood flow to a part of the brain due to occlusion or rupture of an artery to the brain. "ETS-1 was identified as a candidate transcription factor associated with the regulation of gene expression by stroke and NRG1 treatment." (PMID 29856744, 2018). "Using CONFAC, we previously showed that ETS-1 was associated with neuronal death and inflammation in a rat stroke model." (PMID 29856744, 2018). "In line with our results, many genes/proteins such as Hmox1, Gadd45, Ets-1, and Stat3 which are previously shown to be deregulated following stroke were also reported in our study." (PMID 29516010, 2018).
T cell lymphomas (2 papers, 2019 to 2021).
T-cell leukemia (2 papers, 2011 to 2014). A malignant disease of the T-lymphocytes in the bone marrow, thymus, and/or blood. "In addition, the results of a recent study, demonstrating binding of ETS1 on CIP2A promoter in Jurkat T-cell leukemia strongly supports our main conclusion that ETS1 specifically is involved in positive regulation of CIP2A." (PMID 21445343, 2011). "GATA2 and GATA1 are implicated at many (up to 90%) of the TAL1-bound sites in normal hematopoietic cells, and GATA3 along with ETS1 and RUNX1 can direct TAL1 binding when it is aberrantly expressed in T-cell leukemias." (PMID 25319994, 2014).
thyroid (2 papers, 2025). "In contrast, our results show that ETS1 mRNA levels were significantly higher in PTCs with a methylated p16 promoter than in those without, which presents an intriguing dimension to the role of ETS1 in thyroid carcinogenesis." (PMID 40722658, 2025). "The distribution of expression of ETS1 is dependent on the thyroid nonmalignant neoplasia subtype." (PMID 39941022, 2025). "The exploration of the connection between ETS1 and miR-203a-3p/miR-204-3p in the context of PTC is not only significant for elucidating the molecular mechanisms of thyroid carcinogenesis but also for developing targeted therapeutic strategies." (PMID 39941022, 2025). "Exploration of the relation between ETS1, miR-203a-3p, and miR-204-3p in the context of PTC is not only significant for elucidating the molecular mechanisms of thyroid carcinogenesis but also for developing targeted therapeutic strategies." (PMID 39941022, 2025).
uterine cancer (2 papers, 2008 to 2010). Primary or metastatic malignant neoplasm involving the uterine corpus and/or the cervix. "Similar to the studies in uterine cancer, this study also supports a role for expression of Ets-1 in cancer progression that is at least in part mediated by increased angiogenesis." (PMID 20454645, 2010). "In a study of 60 patients with uterine cancer a strong Ets-1 expression was observed in 66% of patients, and was associated with increased tumor microvessel density." (PMID 20454645, 2010). "The angiogenic factors vascular endothelial growth factor (VEGF) and thymidine phosphorylase identified with platelet-derived endothelial cell growth factor and interleukin (IL-8) along with the angiogenic transcriptional factor ETS-1 work on angiogenesis in uterine cancers." (PMID 19002177, 2008).
vitiligo (2 papers, 2024 to 2025). Generalized well circumscribed patches of leukoderma that are generally distributed over symmetric body locations and is due to autoimmune destruction of melanocytes. "The present study, which utilized Ets-1 deficient mice as a model for studying vitiligo, has several limitations." (PMID 41310821, 2025). "Ets-1 gene-deficient mice exhibit a vitiligo-like phenotype with spontaneous skin depigmentation, suggesting a direct link between Ets-1 deficiency and MC dysfunction." (PMID 41310821, 2025). "Reduced skin ETS-1 and ICAM-1 have been linked in patients with vitiligo, and silencing of ETS-1 using small-interfering (si)RNA reduces levels of ICAM1 transcript and ICAM-1 protein in cultured human melanocytes." (PMID 38984117, 2024). "Although Ets-1 deficient mice display a vitiligo-like phenotype, the underlying mechanisms and pathways may not fully replicate those in human vitiligo, limiting the direct applicability of findings from mouse models to human patients." (PMID 41310821, 2025). "This study verifies that the vitiligo-like skin depigmentation in Ets-1 deficient mice may be attributed to Ets-1 gene depletion, which may play a pivotal role in the pathogenesis of vitiligo." (PMID 41310821, 2025). "Alternatively, Ets-1 deficiency may interfere with melanoblast maturation into functional MCs, compromising their survival and ultimately contributing to the pathogenesis of vitiligo." (PMID 41310821, 2025). "Although skin hypopigmentation has previously been reported in Ets-1 null mice, this study is, to our knowledge, the first to characterize the vitiligo-like phenotype in these mice through detailed histological and transcriptomic analyses." (PMID 41310821, 2025). "In the context of vitiligo pathogenesis, Ets-1 downregulation has been previously reported in the skins of vitiligo patients." (PMID 41310821, 2025). "All adult Ets-1 KO mice exhibited characteristics consistent with vitiligo, including a distinct area of white hair on the belly and depigmentation of distal limbs, such as feet and tails." (PMID 41310821, 2025). "Based on these observations, we proposed that the Ets-1 KO mice may serve as a suitable model for studying the pathomechanisms of vitiligo and developing therapeutic strategies." (PMID 41310821, 2025). "The observed downregulation of melanogenesis-related genes and alterations in key signaling pathways provide valuable insights into the molecular basis of Ets-1’s role in MC maintenance and suggest potential therapeutic targets for skin pigmentation disorders, including vitiligo." (PMID 41310821, 2025). "We also propose that the therapeutic effect of topical Ets-1 gene delivery in the depigmented skins of KO mice or topical agonistic treatment could be further studied, which hopefully develop a novel vitiligo treatment tool by restoring its cutaneous expression and function." (PMID 41310821, 2025). "Therefore, future investigations into changes in MC apoptosis and capillary density in Ets-1 KO mice―as well as in human depigmented skin―may help clarify potential cytoprotective and vascular regulatory functions of Ets-1 in vitiligo pathogenesis." (PMID 41310821, 2025). "Despite neither transcription nor translation of Ets-1 was detectable in the MCs isolated from vitiligo patients, the Ets-1 downregulation is proposed to underlie the decreased expression and activity of MMPs and the reduced expression of cell adhesion molecules." (PMID 41310821, 2025). "Notably, the coincident dysregulation observed in both melanogenesis and IL-17 signaling pathways in the depigmented skin lesions of Ets-1 KO mice supports the applicability of this model for studying vitiligo pathomechanisms and developing therapeutics strategies." (PMID 41310821, 2025).
vitiligo (continued). "Although alterations in capillary density have not been widely reported in vitiligo-affected skin, insights from developmental and cancer biology have identified Ets-1 as a significant regulator of vasculogenesis and tumor angiogenesis." (PMID 41310821, 2025).
acne (1 paper, 2024). An inflammatory process of the sebaceous glands which is characterized by comedones, nodules, papules and/or pustules on the skin. "The expression of CXCL10, MMP9, IL1B, CXCL8, and CXCR4 were co-regulated by IRF1, STAT1, STAT3, IKBKB, HDAC1, ETS1, and CEBPB, which were highly expressed in rosacea and acne lesions." (PMID 38321132, 2024).
adenoma (1 paper, 2015). A neoplasm arising from the epithelium. "Neither Ets1 nor Zeb1 were expressed in precancerous AAH or adenomas, but both were expressed at the invasive edge of adenocarcinomas (results not shown)." (PMID 25880398, 2015).
adult T-cell leukemia/lymphoma (1 paper, 2025). A peripheral (mature) T-cell neoplasm linked to the human T-cell leukemia virus type 1 (HTLV-1), adult T-cell leukemia/lymphoma is endemic in several regions of the world, in particular Japan, the Caribbean, and parts of Central Africa. "In adult T-cell leukemia/lymphoma (ATLL), ETS1 is highly expressed in patients of North American descent and promotes tumor growth by regulating CCR4, making it a potential therapeutic target." (PMID 40181983, 2025).
aneurysm (1 paper, 2023). Bulging or ballooning in an area of an artery secondary to arterial wall weakening. "Although the specific molecular players driving aneurysm in intracranial arteries and the aorta may differ, it seems likely that ETS1 has a role also in the formation of aneurysm in other arterial segments." (PMID 37698712, 2023). "Moreover, vascular injury has been associated with a high ETS1 expression, and the simultaneous inhibition of ETS1 and NF-κB in a rabbit model of AAA preserves elastin integrity and reduces aneurysm size." (PMID 37698712, 2023).
benign neoplasms of the brain (1 paper, 2022). "On the other hand, MC4R and ETS1 in benign brain tumor are primarily associated with melanocortin receptor binding and regulating angiogenesis." (PMID 35887658, 2022). "Four signals associated with LRP1B (rs7599907), FRMD3 (rs10121898), MC4R (rs8087522), and ETS1 (rs76404385) identified benign neoplasms of the brain." (PMID 35887658, 2022).
bile duct carcinoma (1 paper, 2016). "Our group independently found that the Ets-1 oncogenic transcription factor directly transactivates the MGAT5 promoter in human bile duct carcinoma cells and that the Ets-1 levels were highly correlated with the levels of GnT-V expression in various cancer cell lines." (PMID 27136596, 2016).
bladder tumor (1 paper, 2016). "Taken together, GATA4 and ETS1 overexpression mediated by MLL mutation enhanced the ability of drug-resistant to epirubicin which endowed mutated bladder tumor cells the advantage of survival and recurrence in the presence of chemotherapeutics." (PMID 26625313, 2016).
breast adenocarcinoma (1 paper, 2018). "In 1833 bone metastatic cells, derived from MDA-MB-231 breast adenocarcinoma cells, the effects of miR-125b on ETS1 activity and on the biological functions are influenced by HGF and hypoxia, which are stimuli of the bone microenvironment." (PMID 29700305, 2018). "In the pro-metastatic cell line 1833, derived from MDA-MB-231 breast adenocarcinoma cells, both hypoxia and hepatocyte growth factor (HGF) influence the effect of miR-125b on ETS proto-oncogene 1 transcription factor (ETS1)." (PMID 29700305, 2018).
Burkitt lymphoma (1 paper, 2021). A rare form of malignant mature B-cell non-Hodgkin lymphoma. "Mutations in ETS1 were found more frequently in Burkitt lymphoma, but only sporadically in DLBLC." (PMID 33479306, 2021).
Castleman disease (1 paper, 2023). Castleman disease (CD) is a benign lymphoproliferative disorder that may present as a localized or multicentric form. "In Castleman disease, improper ETS1, PTPN6, TGFBR2, DNMT3A, and PDGFRB genes cause the appearance of symptoms." (PMID 36766791, 2023).
cervical squamous cell carcinoma (1 paper, 2020). A squamous cell carcinoma arising from the cervical epithelium. "Strikingly, ETS1 is significantly down-regulated in all the gynecologic cancers, including BRCA, cervical squamous cell carcinoma and endocervical, ovarian serous cystadenocarcinoma, uterine corpus endometrial carcinoma, and uterine carcinosarcoma, out of the 33 cancers." (PMID 32412047, 2020).
choroidal melanoma (1 paper, 2008). Malignant tumor of melanocytes of the choroid. "One role for ETS-1 and ETS-2 in ocular cancer and choroidal melanoma may be mediated through their increased transcriptional activity and upregulated expression of their target genes involved in angiogenesis and/or metastatic propagation." (PMID 18958307, 2008). "Thus, ETS-1 and ETS-2 may be involved in the development of this disease and are therefore potential targets for choroidal melanoma gene therapy." (PMID 18958307, 2008). "In conclusion, this study shows that ETS-1 and ETS-2 may play a major role in choroidal melanoma." (PMID 18958307, 2008). "Therefore, upregulation of ETS-1 and ETS-2 could also occur in choroidal melanoma." (PMID 18958307, 2008).
chronic lymphocytic leukemia (1 paper, 2025). "J. Ott and colleagues identified a SE-based CRC in chronic lymphocytic leukemia (CLL) involving PAX5, FOXP1, RARA, ETS1, IRF2, and IRF8, highlighting PAX5's dominant role." (PMID 40083704, 2025).
ciliopathy (1 paper, 2023). A genetic disorder of the cellular cilia or the cilia anchoring structures, the basal bodies, or of ciliary function. "Consistent with the phenotype of ciliopathy patients, disruption of ets1 expression in zebrafish caused body curvature and heart dysfunction." (PMID 37326025, 2023). "To further investigate the potential role of ETS1 in EVC ciliopathy, we performed ETS1 overexpression and knockdown experiments in hTERT RPE-1 cells and observed the impact on cilia formation after serum starvation." (PMID 37326025, 2023). "Our results depict a dynamic landscape of chromatin accessibility in EVC ciliopathy patients, and uncover an insightful role for ETS1 in controlling the global transcriptional program of cilia genes by reprogramming the widespread chromatin state." (PMID 37326025, 2023). "In particular, the ETS1 enrichment signal on CAAs was elevated in EVC ciliopathy patients relative to that in healthy individuals, reinforcing the potential function of ETS1 in modulating the activity of CAAs." (PMID 37326025, 2023). "We also confirmed aberrant ETS1 activation in EVC ciliopathy patients, while suppression of the ETS1-induced open chromatin state collapsed, leading to cilia defects in both cellular and organismal contexts." (PMID 37326025, 2023). "To further determine whether ETS1 maintains the chromatin landscapes, we assessed ETS1 occupancy in PBMCs from both EVC ciliopathy patients and healthy donors by using CUT&Tag." (PMID 37326025, 2023). "Thus, it is reasonable that EVC ciliopathy patients who have enhanced HH signalling induced by ETS1 overexpression exhibit the symptom of polydactyly." (PMID 37326025, 2023). "Altogether, our data support a EVC ciliopathy model in which ETS1 is recruited to CAAs to stabilize the open chromatin state, thereby inducing a genome-wide program of expression of cilia genes related to cilia-associated processes such as signalling transduction." (PMID 37326025, 2023). "Notably, ETS1 displayed a genome-wide signal increase in EVC ciliopathy patients relative to healthy donors." (PMID 37326025, 2023). "In summary, our results provide evidence that ETS1 functions as the important regulator in organ development, the malfunction of which negatively affects the fins and heart, in line with the characteristics of ciliopathies." (PMID 37326025, 2023). "To identify putative TFs that regulate CAAs, we subsequently screened the ETS TFs exhibiting expression changes and found that ETS1 expression—both for mRNA and for protein—was notably higher in EVC ciliopathy patients relative to healthy donors." (PMID 37326025, 2023). "Moreover, a single transcription factor, ETS1, can be recruited to CAAs, leading to prominent chromatin accessibility reconstruction in EVC ciliopathy patients." (PMID 37326025, 2023). "Collectively, our findings reveal the role of ETS1-driven chromatin accessibility redistribution in the regulatory network modulation of critical cilia genes, indicating a novel appendage-patterning pathway previously unrecognized in EVC ciliopathy pathogenesis." (PMID 37326025, 2023). "Additionally, the closed chromatin regions in ETS1 knockdown cells were generally anti-correlated with accessibility changes in CAAs, highlighting the function of ETS1 in restructuring chromatin accessibility during EVC ciliopathy pathogenesis." (PMID 37326025, 2023).